UTP14A (UTP14A small subunit processome component)
Description:
May be required for ribosome biogenesis.
Synonyms: SDCCAG16; NY-CO-16; Utp14; NYCO16; dJ537K23.3
Tractability: Small molecule: a structure with a bound ligand is known. PROTAC: UniProt records ubiquitination sites on it; ubiquitination databases record sites on it; its protein half-life has been measured.
Gene: Protein-coding gene on chromosome X (129,906,121 to 129,929,761, forward strand). Ensembl gene ENSG00000156697.
Subcellular location: Nucleus, nucleolus
Subcellular location (Human Protein Atlas): Nucleoli; Cytosol
Pathways (Reactome):
Metabolism of RNA: Major pathway of rRNA processing in the nucleolus and cytosol; rRNA modification in the nucleus and cytosol
Gene Ontology:
Molecular function: protein binding; RNA binding
Biological process: protein localization to nucleolus; ribosomal small subunit biogenesis; maturation of SSU-rRNA; rRNA processing
Cellular component: nucleolus; nucleoplasm; small-subunit processome
Homologues: Orthologues: chimpanzee UTP14A (99% identical), macaque UTP14A (97% identical), dog UTP14A (84% identical), mouse Utp14a (77% identical), rat Utp14a (77% identical), rat LOC102551819 (71% identical), mouse Utp14b (68% identical), tropical clawed frog utp14a (50% identical), zebrafish UTP14A (46% identical), Drosophila melanogaster CG12301 (28% identical), Caenorhabditis elegans F27C1.6 (23% identical). Paralogues in human: UTP14C (90% identical).
Diseases named in the same sentence as UTP14A in open-access papers:
UTP14A is named in the same sentence as 12 diseases in open-access papers, as found by Europe PMC text mining. Sharing a sentence is not in itself a finding about the gene and the disease. The quoted sentences say what the papers report.
colorectal cancer (3 papers, 2019 to 2024). A primary or metastatic malignant neoplasm that affects the colon or rectum. "UTP14A (U three protein 14A) plays a key role in the synthesis of ribosomes and 18S rRNA; however, in the last few years, data have appeared on the association of this gene with some types of tumors—hepatocellular carcinoma, colorectal carcinoma, and esophageal squamous cell carcinoma." (PMID 38540309, 2024). "It has been noted that UTP14A is involved in the development of colorectal cancer by promoting angiogenesis, while the inhibition of UTP14A can improve the prognosis of patients." (PMID 35734237, 2022).
esophageal cancer (1 paper, 2022). A primary or metastatic malignant neoplasm involving the esophagus. "The upregulation of UTP14A was associated with the progression of esophageal cancer." (PMID 35734237, 2022).
Obesity (1 paper, 2022). Accumulation of substantial excess body fat. "UTP14A, DKC1, DDX10, PinX1, and ESF1 have been identified as hub genes in obesity-induced pathological changes in the heart and may be involved in obesity-induced cardiac injury by affecting cardiac microcirculatory function." (PMID 35734237, 2022).
cancer (3 papers, 2019 to 2022). A tumor composed of atypical neoplastic, often pleomorphic cells that invade other tissues. "The corresponding 210 tissue samples and 30 cancer‐distant mucosa (CDM) samples were tested for UTP14a expression by immunohistochemical staining." (PMID 31496055, 2019). "Survival analysis examining high expression levels of three of these genes (UBE2A, MAGEA2 and UTP14A) corresponded with poorer survival in five different cancers." (PMID 31772231, 2019). "In addition, EXOSC5, UTP14A, TWISTNB, and TBL3 were closely related to the occurrence or prognosis of several cancers." (PMID 35601016, 2022). "Our results suggest that UTP14a is aberrantly expressed in ESCC, plays a critical role in cancer progression and could be a potential prognosis predictor of ESCC." (PMID 31496055, 2019).
tumor (3 papers, 2019 to 2024). "High expression of UTP14a in ESCC was significantly correlated with the pT stage and pTNM stage; overexpression of UTP14a indicated an increased risk of tumor proliferation and invasion." (PMID 31496055, 2019). "Taken together, these data suggest that UTP14A is essential to promote tumour growth via the PERK pathway in vivo and in vitro." (PMID 33391409, 2021). "When downregulation of UTP14A significantly increased the apoptotic rate of tumour cells, while overexpression of UTP14A reduced apoptosis." (PMID 33391409, 2021). "The PERK/eIF2a signalling pathway was positively regulated by UTP14A, and its tumour-promoting effect was further activated by overexpression of UTP14A." (PMID 33391409, 2021). "High expression of UTP14a in ESCC correlated significantly with tumor invasive depth and predicts poor survival; in vitro experiments demonstrated that UTP14a inhibits cell proliferation and invasion." (PMID 31496055, 2019). "High expression of UTP14a in ESCC correlated significantly with tumor invasive depth (pT stage), which predicts poor disease‐free survival and disease‐specific survival, as indicated by the log‐rank test and Cox proportional hazards regression analysis." (PMID 31496055, 2019). "They demonstrated that UTP14a forms a complex with USP36/Fbw7γ, stabilizes c‐Myc in the nucleolus, and inhibits c‐Myc degradation; knockdown of UTP14a leads to a decrease in c‐Myc levels and inhibits tumor growth." (PMID 31496055, 2019). "In conclusion, our results suggest that UTP14a expression is correlated with tumor proliferation and invasion; higher expression of UTP14a is a predictor of poor prognosis in patients with ESCC." (PMID 31496055, 2019). "High expression of UTP14a in ESCC was significantly correlated with postoperative tumor invasive depth (pT stage) (P = 0.005) and advanced TNM stage (P = 0.001)." (PMID 31496055, 2019). "In ESCC tissues, UTP14a was mainly located in the cytoplasm of tumor cells, and only a small part was located in the nuclei." (PMID 31496055, 2019). "In this study, we investigated the mechanism by which UTP14A promotes tumour progression in ESCC." (PMID 33391409, 2021). "To further study the role and mechanism of UTP14A in tumour metastasis by in vitro experiments, we tested the protein and mRNA expression of UTP14A in several commonly used ESCC cell lines, among which KYSE-150 cells and Eca109 cells had relatively higher expression." (PMID 33391409, 2021). "To further verify whether the effect of UTP14A on ESCC cells was achieved by regulating the expression of PERK, we observed the effects of PERK knockdown on tumour cells and whether this effect was regulated by UTP14A." (PMID 33391409, 2021). "Next, we used GSK2606414 to inhibit PERK expression and investigated whether UTP14A regulates tumour growth through PERK." (PMID 33391409, 2021). "We speculate that UTP14a might work as a tumor promoter through the cell proliferation and cell invasion pathways, but this hypothesis requires confirmation by further studies." (PMID 31496055, 2019). "As a tumor suppressor, P16 simultaneously inhibits RB1 phosphorylation and destabilizes RB1 via UTP14a-catalyzed K810 ubiquitination." (PMID 39351198, 2024).
UTP14A also shares sentences with these, for which no sentence is quoted: esophageal squamous cell carcinoma (2 papers); hepatocellular carcinoma (2); Infertility (1); Insulin resistance (1); male fertility (1); scleroderma (1); Zinc deficiency (1).